IGF2BP3 (insulin like growth factor 2 mRNA binding protein 3)
Diseases named in the same sentence as IGF2BP3 in open-access papers (continued):
Sharing a sentence is not in itself a finding about the gene and the disease.
breast carcinoma (continued). "There is currently no established systematic explanation of the clinical application and diagnostic value of insulin-like growth factor 2 mRNA-binding protein 3 (IGF2BP3) in breast cancer." (PMID 40672753, 2025). "We will use immunohistochemistry (IHC) to analyze the IGF2BP3 protein expression in 299 cases of breast cancer." (PMID 40672753, 2025). "The ROC curve analysis showed that the area under the curve (AUC) for IGF2BP3 positive prediction of breast cancer was 0.557 (95% CI 0.483–0.631; P=0.164), with a sensitivity of 11.4%, specificity of 100.0%, PPV of 100.0%, and NPV of 18.5%." (PMID 40672753, 2025). "For instance, the METTL3/IGF2BP3 axis-mediated stabilization of PD-L1 mRNA suppresses anti-tumor immunity in breast cancer." (PMID 40279954, 2025). "In this study, we aim to investigate the expression of IGF2BP3 in breast cancer tissues and its clinical significance." (PMID 40672753, 2025). "The results showed that the performance of IGF2BP3 in the differential diagnosis of breast cancer was limited, with an AUC of 0.557." (PMID 40672753, 2025). "To further verify the relationship between IGF2BP3 expression and lymph node metastasis, we examined the postoperative pathological results of breast cancer cases." (PMID 40672753, 2025). "The IGF2BP3 positivity rate in breast cancer tissues was significantly higher than in normal breast tissues (P=0.006)." (PMID 40672753, 2025). "In conclusion, these findings suggest that IGF2BP3 has the potential to be a biomarker for identifying more aggressive subtypes of breast cancer, particularly TNBC, and it has good clinical value in diagnosing TNBC." (PMID 40672753, 2025). "Conversely, the presence of IGF2BP3 was less common in breast cancer cases with axillary lymph node metastasis and advanced tumor stage (both P<0.05)." (PMID 40672753, 2025). "Our results showed that the positivity rate of IGF2BP3 in breast cancer tissues was 11.4% (34/299), significantly higher than that in normal breast tissues (0.0%, 0/60) (P=0.006)." (PMID 40672753, 2025). "The MYC-activated IGF2BP3 gene regulates the proliferation, invasion, and metastasis ability of nasopharyngeal and breast carcinoma cells." (PMID 38992083, 2024). "By reviewing the literature, we learned that inhibiting IGF2BP3 in breast cancer cells can enhance anti-tumor immunity through PD-L1-mediated T cell activation, exhaustion, and infiltration." (PMID 38577615, 2024). "IGF2BP3 inhibits immune surveillance of breast cancer by recognizing m6A modification on PDL-1 and enhancing its mRNA stability." (PMID 38632251, 2024). "lncRNA CERS6-AS1 promotes the stability of CERS6 mRNA by combining with IGF2BP3, thereby promoting breast cancer cell proliferation and inhibiting cell apoptosis." (PMID 37298373, 2023). "A recent study demonstrated that PD-L1 expression is positively correlated with the expression of METTL3 and IGF2BP3 in breast cancer." (PMID 36960074, 2023). "TCGA cohorts were analysed for IGF2BP3 expression and IGF2BP3 promoter methylation levels in different breast cancer subtypes." (PMID 37743642, 2023). "IGF2BP3 expression is increased in breast cancer stem cells, which contributes to the self-renewal of tumors." (PMID 37298373, 2023). "In summary, IGF2BP3 promotes tumor progression through multiple pathways in breast cancer, including increased chemotherapeutic drug resistance and tumor immune escape." (PMID 37298373, 2023). "Specifically, IGF2BP3 was reported to be associated with PD-L1 and promote stabilization of PD-L1 mRNA by METTL3-mediated m6A modification in breast cancer." (PMID 38171932, 2023). "Recent studies have shown that IGF2BP3 exerts an oncogenic role via m6A modification in many cancers, such as colon cancer 41, bladder cancer 42, and breast cancer." (PMID 37056932, 2023). "The knockdown of METTL3/IGF2BP3 can enhance T cell-mediated antitumor immunity by downregulating PD-L1 expression, thus inhibiting the progression of breast cancer." (PMID 37298373, 2023).
breast carcinoma (continued). "IGF2BP3 is a factor promoting many kinds of tumors and plays a cancer-promoting role in breast cancer." (PMID 37298373, 2023). "PD-L1 expression was also positively correlated with METTL3 and IGF2BP3 expression in breast cancer tissues." (PMID 35197058, 2022). "Basal-like subtypes and other breast cancer subtypes are associated with the m6A regulators YTHDC2, IGF2BP2, IGF2BP3 and RBM15, and luminal A and B subtypes are classified into two clusters according to the methylation status of these four regulators." (PMID 35721510, 2022). "Correspondingly, we also found that IGF2BP3 knockdown was necessary to promote T cell-induced immune attack in breast cancer cells." (PMID 35197058, 2022). "IGF2BP3 also affects tumor immune surveillance and immune infiltration in breast cancer and renal cell carcinoma." (PMID 36313631, 2022). "A recent study found that the regulation of SLUG by IGF2BP3 plays a crucial role in maintaining the stem cell properties of breast cancer cells." (PMID 36686749, 2022). "METTL3 was demonstrated to upregulate PD-L1 expression via IGF2BP3 by m6A-dependent manner to modulate immune surveillance in breast cancer." (PMID 35721510, 2022). "The results also showed that PD-L1 mRNA levels increased upon IGF2BP3 overexpression and decreased when IGF2BP3 was knocked down in breast cancer cell lines." (PMID 35197058, 2022). "The total protein and membrane expressions of PD-L1 were remarkably reduced upon IGF2BP3 disruption in breast cancer cells." (PMID 35197058, 2022). "For instance, lncRNA CERS6-AS1 plays a cancer-promoting role in breast cancer via recruiting IGF2BP3 to strengthen the stability of CERS6 mRNA." (PMID 35173610, 2021). "Numerous cancers have been identified the overexpression of IGF2BP3 including lung cancer, breast cancer, colorectal cancer, hepatocellular carcinoma, pancreatic cancer, glioblastoma and ovarian clear cell carcinoma." (PMID 32984260, 2020). "As to IGF2BP3, despite the comparable expression between breast cancer and normal samples in our data, its expression in basal-like subtype was significantly higher than that in other subtypes." (PMID 33585234, 2020). "In breast cancer, apart from the capability of elevating the invasive potential, IGF2BP3 was also believed to be involved in chemo-resistance by stabilizing the mRNA of breast cancer resistance protein (ABCG2)." (PMID 28399871, 2017). "In a multiple logistic regression analysis, the independent predictors of IGF2BP3 expression in breast cancer were TNBC status (odds ratio = 3.408; 95% confidence interval: 1.026–11.321; P=0.045) and axillary lymph node metastasis (0.200; 0.068–0.593; P=0.004)." (PMID 40672753, 2025). "Understanding the role of IGF2BP3 may lead to the development of novel targeted therapies for breast cancer patients, particularly those with TNBC who currently have limited treatment options." (PMID 40672753, 2025). "The results of the multiple logistic regression analysis showed that TNBC status (odds ratio [OR] = 3.408; 95% confidence interval [CI]: 1.026–11.321; P=0.045) and axillary lymph node metastasis (0.200; 0.068–0.593; P=0.004) were the independent predictors of IGF2BP3 expression in breast cancer." (PMID 40672753, 2025). "Moreover,Tumor immune monitoring is inhibited by IGF2BP3 through targeting breast cancer PD-L1 mRNA." (PMID 38355626, 2024). "IGF2BP3 is also involved in the immune escape of breast cancer cells." (PMID 37298373, 2023). "Additionally, the METTL3/IGF2BP3 axis reinforces the immune evasion capacity of breast cancer cells in the TME through increasing the stability of downstream target PD-L1 mRNA and the expression of its transmembrane protein." (PMID 37280679, 2023). "This suggests that methylation may regulate the expression of IGF2BP3 in some breast cancer patients." (PMID 37298373, 2023). "Our results suggested that PD-L1 could be a key mediator of METTL3/IGF2BP3-induced tumor immune surveillance in breast cancer cells." (PMID 35197058, 2022).
breast carcinoma (continued). "We identified that only IGF2BP3 could significantly decrease the expression and stability of PD-L1 in breast cancer cells." (PMID 35197058, 2022). "Collectively, these clinical sample data also verified that the expressions of METTL3 and IGF2BP3 were positively correlated with PD-L1 and indicated that PD-L1 could be a potential downstream target of the METTL3/IGF2BP3 axis in breast cancer." (PMID 35197058, 2022). "IGF2BP3 served as an antagonism could inhibit miRNA-3614 maturation, mediately resulted in preventing breast cancer cell growth through downregulating TRIM25." (PMID 34338136, 2021). "Emerging evidence has shown that IGF2BP3 is highly expressed in breast cancer." (PMID 34044876, 2021). "In breast cancer cells, IGF2BP3 has a direct correlation with E-cadherin, vimentin, and Slug (P < 0.05) and further promotes invasion and migration by prompting the EMT83 and reducing cell apoptosis by activating the Hedgehog signalling pathway CD44/CD44+Fbs/IGF2." (PMID 34044876, 2021). "In addition, IGF2BP3 promotes CERS6 mRNA stability, which is associated with increased expression of CERS6 and a number of malignant behaviors of breast cancer mediated by CERS6." (PMID 33228740, 2020). "Finally, we came to a conclusion that CERS6‐AS1 functions as a malignancy promoter in breast cancer by binding to IGF2BP3 to enhance the stability of CERS6 mRNA." (PMID 31701672, 2020). "In particular, IGF2BP3 can exert its effects by destabilizing miR145-5p, thus favoring the function of breast cancer stem cells (CSCs), or by stabilizing the lncRNA LINC01138, thus sustaining the proliferation and invasion abilities of hepatocellular carcinoma cells." (PMID 32010687, 2019). "In addition, IGF2BP3 sustains SNAI (Slug) mRNA translation in breast cancer cells, putatively preventing its miRNA-mediated decay; in turn, SNAI favors the transcription of the stem cell factor SOX2." (PMID 32010687, 2019). "However, a systematic explanation of the clinical application and diagnostic value of IGF2BP3 in breast cancer has not been achieved, mainly due to limited sample sizes in some studies or insufficient comprehensive clinicopathological correlation analyses." (PMID 40672753, 2025). "Therefore, it may be one of the explanations for the low incidence of lymph node metastasis in breast cancer with positive IGF2BP3 expression." (PMID 40672753, 2025). "Furthermore, in breast cancer, IGF2BP3 could inhibit miRNA-3614 maturation and protect TRIM25 mRNA from degradation to promote breast cancer cell proliferation." (PMID 37407973, 2023). "LDH release assay showed that METTL3-, IGF2BP3-knockdown and atezolizumab (anti-PD-L1) treatment increased the breast cancer cell sensitivity towards T-cell killing as compared to control groups, and these effects could be reversed by the overexpression of PD-L1." (PMID 35197058, 2022). "It has been reported that IGF2BP3, a well-known oncoprotein, is post-transcriptionally active and is involved in tumor growth, metastasis, survival, and chemo-resistance in the gastric, liver, and breast cancers and self-renewal and tumor initiation in cancer stem cells." (PMID 35197058, 2022). "To assess the potential impact of IGF2BP3 expression on patient survival, we analyzed IGF2BP3 expression in relation to RFS, DMFS and OS rates in patients with breast cancer." (PMID 40672753, 2025). "A comparison of expression levels across breast cancer subtypes revealed an upregulation of the readers IGF2BP1, IGF2BP2, and IGF2BP3 in basal cases, whereas other m6A readers manifested a more homogeneous expression across subtypes." (PMID 40918643, 2025). "The KIAA1429 protein interacts with the IGF2BP3 (insulin-like growth factor 2 mRNA-binding protein 3) protein, and then binds to and stabilizes m6A-modified HAS2 mRNA in breast cancer." (PMID 39456252, 2024).
breast carcinoma (continued). "For example, in breast cancer, METTL3-mediated activation of PD-L1 mRNA is IGF2BP3-dependent, the METTL3/IGF2BP3 axis upregulates the m6A modification of PD-L1 mRNA, further increasing the stability of PD-L1 mRNA and inhibiting tumor immune surveillance." (PMID 38762484, 2024). "In breast cancer, METTL3 expression increased PD-L1 stability and expression, and METTL3/IGF2BP3 knockdown significantly enhanced the immune response." (PMID 39033180, 2024). "In breast cancer, high expression of METTL3 and IGF2BP3 maintains PD-L1 mRNA stability, promotes T cell senescence, and evades immune surveillance." (PMID 39033180, 2024). "Targeting regulators such as METTL3, METTL14, IGF2BP3, or YTHDF1 can alleviate T-cell suppression in melanoma, colorectal cancer, non-small cell lung cancer (NSCLC), and breast cancer." (PMID 39372415, 2024). "IGF2BP3 was found to target SLUG mRNA to prevent decay, thereby participating in the regulation of breast cancer progression." (PMID 37298373, 2023). "IGF2BP3 stabilizes WNT5B mRNA by inhibiting the expression of miR145-5p, thereby promoting breast cancer progression." (PMID 37298373, 2023). "IGF2BP3 and miR-3614-3p can competitively bind TRIM25 mRNA, thus protecting TRIM25 mRNA from degradation and promoting breast cancer cell proliferation." (PMID 37298373, 2023). "The results indicated that IGF2BP3 expression was positively correlated with infiltration of CD8+, CD4+ T cells, and B cells in each of the breast cancer subtypes, which was similar to the effect of PD-L1 (CD274)." (PMID 35197058, 2022). "Taken together, the present study on METTL3/IGF2BP3-mediated N6-methyladenosine modification of PD-L1 mRNA and antitumor immunity provided a novel mechanism for m6A regulator-induced immunosuppression in breast cancer, which may have potential application as a novel therapeutic target." (PMID 35197058, 2022). "In breast cancer, eight genes (METTL3, KIAA1429, ZC3H13, FTO, YTHDF1, YTHDF2, IGF2BP2, and IGF2BP3) were significantly enriched in tumor cells compared to immune or stromal cells." (PMID 35794212, 2022). "With the increase of malignancy of breast cancer, the expression level of several m6A RNA methylation regulators, such as FTO, HNRNPA2B1 YTHDC1, IGF2BP1, IGF2BP2 and IGF2BP3, decreased or increased." (PMID 34141492, 2021). "After comparing breast cancer tissues with adjacent normal tissues, we found IGF2BP1 and IGF2BP3 had a fold change >2 in breast cancer tissues." (PMID 34141492, 2021). "It has been identified that IGF2BP3 can inhibit miRNA-3614 maturation thereby increased TRIM25 expression and promotes the cell proliferation of breast cancer." (PMID 32984260, 2020). "Our further research for the molecular mechanism showed that IGF2BP3 bound to CD44 mRNA and enhanced CD44 expression, which increased IGF2 levels of fibroblasts and then stimulated breast cancer cell proliferation and drug resistance." (PMID 28523716, 2017). "In conclusion, the results illustrated that in CD44+Fbs, binding of IGF2BP3 and CD44 promotes IGF2 expression and then accelerates breast cancer cell proliferation, survival and induced chemotherapy resistance likely by activating Hedgehog signal pathways." (PMID 28523716, 2017). "IGF2BP3 levels were found to be elevated in breast cancer cases with higher tumor grade, ER negative, PR negative, HER2 negative, higher Ki-67 index, and the triple-negative breast cancer (TNBC) molecular subtype (all P<0.05)." (PMID 40672753, 2025). "Furthermore, the positivity rates of IGF2BP3 in stage I, II, and III breast cancer were 15.1% (13/86), 13.2% (20/151), and 1.6% (1/62) respectively, with a statistically significant difference between groups (P=0.023)." (PMID 40672753, 2025). "In breast cancer (BRCA), the model selected HNRNPC, IGF2BP2, IGF2BP3, FTO, METTL16, and ALKBH1." (PMID 40565233, 2025).
breast carcinoma (continued). "Additionally, we used the tissue microarray of breast cancer and found that METTL3, IGF2BP3, and PD-L1 were positively correlated by IHC staining." (PMID 35197058, 2022). "In addition, breast cancer tissue microarray was used to analyze the correlation between PD-L1 and METTL3 or IGF2BP3 expression." (PMID 35197058, 2022). "In triple-negative breast cancer, IGF2BP3 and IGF2BP2 synergistically recruited CNOT1 complex, reduced the stability of progesterone receptor and ultimately promoted the migration and metastasis of breast cancer." (PMID 35676262, 2022). "Additionally, PD-L1-positive tissues expressed higher levels of METTL3 and PD-L1-negative tissues showed a concomitant decrease in IGF2BP3 expression, which suggested the existence of a METTL3-IGF2BP3-PD-L1 regulating axis in breast cancer." (PMID 35197058, 2022). "IGF2BP1, IGF2BP2 and IGF2BP3, members of the IGF2BP family, modulate RNA splicing, translation, processing, and stability and thereby affect cell proliferation, differentiation, invasion and metastasis in breast cancer." (PMID 34044876, 2021). "This analysis has revealed a number of intact transcripts that are massively upregulated by recurrent geneUIB fusions, including IGF2 in colorectal, ETV1 in prostate, IGF2BP3 in thyroid, and ANO3, LIPG, FUT5, and RSG9 in breast cancers (ordered by the expression fold change within a tumor type)." (PMID 32631391, 2020). "Different from IGF2BP2 and IGF2BP3, although the oncogenic roles of YTHDC2 and RBM15 have been identified in colon cancer and acute megakaryoblastic leukemia, their functions in breast cancer await to be identified." (PMID 33585234, 2020). "Furthermore, the positivity rate of IGF2BP3 in HER2 negative (0-1+) breast cancer patients (19.6%, 27/138) was significantly higher compared to patients with HER2 equivocal (2+) (5.5%, 5/91) and HER2 positive (3+) (2.9%, 2/70) (P<0.001)." (PMID 40672753, 2025). "Interestingly, we found that the positivity rate of IGF2BP3 in breast cancer without axillary lymph node metastasis (18.6%, 29/156) was significantly higher than that in patients with axillary lymph node metastasis (3.5%, 5/143) (P<0.001)." (PMID 40672753, 2025). "Conversely, within the context of breast cancer, the m6A modification catalyzed by METTL3 not only bolsters the longevity of PD-L1 mRNA transcripts but also facilitates their transcriptional activation, a process that hinges on the recognition of the m6A mark by the IGF2BP3 protein." (PMID 39372415, 2024). "In all breast cancer or TNBC patients, no clear relationship between patient prognosis and IGF2BP3 expression was observed." (PMID 40672753, 2025). "However, there are limitations in the study of IGF2BP3 in breast cancer, including a retrospective design that may introduce biases, lack of functional studies on IGF2BP3’s role in cancer progression, limited evidence for its prognostic value, and the relatively small number of positive cases." (PMID 40672753, 2025).